RACK1 (receptor for activated C kinase 1)
Diseases named in the same sentence as RACK1 in open-access papers (continued):
Sharing a sentence is not in itself a finding about the gene and the disease.
melanoma (continued). "RACK1 protein was detected with intense, diffuse and homogenous staining in MITF-positive cells of equine melanomas." (PMID 22747534, 2012). "In this study, we reported that RACK1 was highly expressed in melanoma tissues compared with matched nontumorous skin tissues." (PMID 31949482, 2020). "Comparative expression analysis revealed that the RACK1 gene is overexpressed in melanoma metastases compared to normal melanocytes." (PMID 31717496, 2019). "Primary melanoma cells were harvested from Tyr:NRasQ61K; Pax3GFP/+ mice, with or without the Tyr:Rack1-HA transgene." (PMID 28765829, 2017). "In summary, overexpression of RACK1 was detected in human melanoma with no apparent changes between cutaneous lesions and metastatic melanoma." (PMID 18442364, 2008). "Among melanomas (n = 9), two samples also stained heterogeneously for RACK1 (data not shown)." (PMID 22747534, 2012). "Hence, it is plausible that RACK1 upregulation in melanomas, once established, does not depend on environmental signals provided by stromal cells but is stably inherited from cell to cell." (PMID 18442364, 2008). "By contrast, in cutaneous melanoma, whether superficial spreading melanoma or recurrent dermal melanoma, MITF+ fusiform dermal cells as well as dermal nest of melanocytic cells displayed a strong RACK1 cytoplasmic signal which was homogeneous over the whole lesion (F respectively)." (PMID 18442364, 2008). "No nuclear RACK1 labelling was found in these melanoma samples." (PMID 18442364, 2008). "It is worth noting that, the significantly correlation of RACK1 overexpression with metastasis of melanoma patients has not been found in our study, which may be due to tumor heterogeneity and the limited samples used here, it is necessary to further study in a larger sample size." (PMID 31949482, 2020). "However, the role of RACK1 in melanoma has not yet been reported." (PMID 31949482, 2020).
Alzheimer disease (12 papers, 2011 to 2026). A progressive, neurodegenerative disease characterized by loss of function and death of nerve cells in several areas of the brain leading to loss of cognitive function such as memory and language. "Indeed, aberrant RACK1 expression has been implicated in disorders such as Alzheimer's disease and cancer." (PMID 38689280, 2024). "Another illustration comes from Alzheimer’s disease pathology, where Aβ oligomers reduce RACK1 distribution in the membrane fraction of cortical neurons." (PMID 41373878, 2025). "The receptor for activated C kinase 1 (RACK1) is a protein that plays a crucial role in various signaling pathways and is involved in the pathogenesis of Alzheimer's disease (AD), a prevalent neurodegenerative disease." (PMID 38410996, 2024). "Overexpression of amyloid-β in cortical neuron cultures disrupts the membrane distribution of RACK1, thus it is likely that disruption of the RACK1-PKC complex by amyloid-β contributes to the pathology of Alzheimer's disease." (PMID 33584282, 2020). "Receptors for activated C kinase 1 (RACK1) is reported to directly interact with the M1 mAChR, and the expression of RACK1 is also decreased in the cortex of Alzheimer's disease post-mortem brain tissues compared to healthy aged brain tissues." (PMID 33584282, 2020). "Indeed aberrant RACK1 expression is reported in disease states such as Alzheimer's disease, Down's syndrome, and cancer, and RACK1 expression is known to decrease with age in the rat brain and human leukocytes." (PMID 30112187, 2018). "In addition, RACK1 levels are significantly reduced in aged rats, and decreased RACK1 expression is reported in post-mortem brains of Alzheimer's disease (AD) patients." (PMID 21978545, 2011).
colorectal cancer (9 papers, 2008 to 2026). A primary or metastatic malignant neoplasm that affects the colon or rectum. "Research shows that RACK1 protein is associated with the development of colorectal cancer." (PMID 39251538, 2024). "RACK1 mRNA was also highly expressed in 11 cases of colorectal cancer, with a stronger expression in carcinoma cells than in the stroma." (PMID 18442364, 2008). "Besides, recent studies have also shown that IBA promotes colorectal cancer metastasis by activating RACK1." (PMID 39251538, 2024). "In gastric and colorectal cancer, RACK1 is reported to be a tumour suppresser." (PMID 35101055, 2022). "Recent studies have shown that IBA promotes colorectal cancer metastasis by activating RACK1, highlighting the key interaction between IBA and RACK1." (PMID 39251538, 2024). "However, the role of RACK1 in the pathogenesis of colorectal cancer (CRC) has not been clearly defined." (PMID 30962803, 2019).
neuroblastoma (9 papers, 2013 to 2024). Neuroblastoma (NB) is the most common solid, extracranial childhood tumor. "As we previously reported that ribosomal RACK1 regulates the translation of mRNAs encoding cell cycle genes in neuroblastoma cells and β-actin mRNA in neuronal growth cones, we wondered if the increase in PSD-95 expression occurred at the translational level." (PMID 36233159, 2022). "Rack1 deficiency can inhibit the proliferation and migration of neuroblastoma in vitro." (PMID 34480519, 2021). "The upregulation of genes BSG/CD147, CCDC125, GABRB3, GNB2L1/RACK1, HAPLN4, HEBP2, and HSD17B12 is associated with poor neuroblastoma prognosis and low EFS." (PMID 38398114, 2024). "For example, puromycin incorporation experiments in SH‐SY5Y neuroblastoma cells showed that increased cytoplasmic TDP‐43 reduces global translation through interactions with RACK1 on polyribosomes." (PMID 39185703, 2024). "In particular, TDP-43ΔNLS has been shown to suppress global translation through interaction with ribosome-bound RACK1 in neuroblastoma SH-SY5Y cells." (PMID 38111057, 2023). "In line with this suggestion, it has been shown that ribosomal RACK1 regulates the cell cycle of neuroblastoma and hepatocarcinoma cells, by modulating the translation of the cell cycle and survival genes." (PMID 36233159, 2022). "Recently, puromycin incorporation experiments in SH-SY5Y neuroblastoma cells showed that increased cytoplasmic TDP-43 reduces global translation through interactions with RACK1 on polyribosomes." (PMID 33762006, 2021). "To confirm and extend a previous finding that cytoplasmic TDP-43 co-aggregates with RACK1 in the neuroblastoma cell line SH-SY5Y, we transiently transfected HEK293T cells with HA-tagged wild-type (WT) TDP-43 or a nuclear localization signal (NLS)-deficient mutant of TDP-43, TDP-43ΔNLS." (PMID 38111057, 2023). "This hypothesis is supported by our results where the binding of FMRP to the RACK1 mutant in SH-SY5Y neuroblastoma cells decreases the level of FMRP on ribosomes and polyribosomes." (PMID 36233159, 2022). "To do so, we used the neuroblastoma SH-SY5Y cells as a cell model system and utilized “interactomics” approach in which RACK1 was immunoprecipitated (IPed) following activation of cAMP signaling by the adenylate cyclase activator, forskolin (FSK)." (PMID 27505161, 2016).
ovarian carcinoma (8 papers, 2019 to 2025). A malignant neoplasm originating from the surface ovarian epithelium. "Treatment with a PARP14 inhibitor or mutation of the sites of MARylation on RACK1 blocks these outcomes, as well as the growth of ovarian cancer cells in culture and in vivo." (PMID 39760726, 2025). "Furthermore, the pivotal role of SMURF2 in the pathogenesis of ovarian cancer underlines its essential function as an E3 ubiquitin ligase for RACK1." (PMID 39697237, 2024). "Collectively, our results support a PARP14/TARG1-regulated RACK1 MARylation cycle that controls stress granule assembly and disassembly in ovarian cancer cells." (PMID 39760726, 2025). "We previously identified sites of MARylation on RACK1 in ovarian cancer cells using mass spectrometry–based proteomics (Asp 144, Glu 145, and Asp 203)." (PMID 39760726, 2025). "We observed similar regulation of PARP14-mediated RACK1 MARylation and stress granule assembly in additional ovarian cancer cell lines, SKOV3 and HCC5044 (note the reduced number of discrete G3BP1 puncta upon PARP14i treatment)." (PMID 39760726, 2025). "Herein, we demonstrate that PARP14 is a MART that MARylates RACK1 in ovarian cancer cells to control stress granule formation and the regulation of translation under cellular stress conditions." (PMID 39760726, 2025). "Together, these data show that PARP14-mediated, site-specific MARylation of RACK1 drives stress granule assembly in ovarian cancer cells." (PMID 39760726, 2025). "Herein, we confirmed that RACK1 is MARylated in OVCAR3 ovarian cancer cells using immunoprecipitation of endogenous RACK1, followed by immunoblotting with an antibody-like MAR detection reagent." (PMID 39760726, 2025). "Ovarian cancer cells expressing RACK1-Mut or treated with PARP14i exhibited slower growth than cells expressing RACK1-WT or treated with vehicle in the presence of thapsigargin or carboplatin." (PMID 39760726, 2025). "This action unveils a reciprocal expression pattern between SMURF2 and RACK1, with ovarian cancer manifestations displaying lower SMURF2 levels correlating with diminished RACK1 ubiquitination." (PMID 39697237, 2024). "Receptor for activated C kinase 1 (RACK1) has been confirmed to take part in multiple biological events and the mechanism supporting abnormal RACK1 expression in ovarian cancer (OC) remains to be characterized." (PMID 37828084, 2023). "SMURF2 was abnormal low expression in human ovarian cancer, resulting in decreased ubiquitination of RACK1 and increased stability, which promoted OC progression, and strongly associated with poor patients’ prognosis." (PMID 37828084, 2023). "We observed that RACK1 is MARylated by PARP14 in ovarian cancer cells." (PMID 39760726, 2025). "Our results demonstrate that RACK1 controls the translation of proteins that play an important role in ovarian cancer biology, although the mechanisms through which translation is regulated remain unknown." (PMID 39760726, 2025). "Since our initial results showed that site-specific MARylation of RACK1 controls the translation of mRNAs that are important for the survival of ovarian cancer cells (i.e., AKT1), we sought to explore the possible role of TARG1 in the regulation of translation." (PMID 39760726, 2025). "Herein, we demonstrate that RACK1, an integral component of the ribosome, is MARylated by the mono(ADP-ribosyl) transferase (MART) PARP14 in ovarian cancer cells." (PMID 39760726, 2025). "Our studies thus far have demonstrated that site-specific MARylation of RACK1 mediated by PARP14 is required for stress granule assembly and stress responses in ovarian cancer cells." (PMID 39760726, 2025). "RACK1 promotes the phosphorylation of Akt and MAPK, as well as the proliferation, migration, and invasion of ovarian cancer cells." (PMID 31474227, 2019).
ovarian carcinoma (continued). "In this regard, we observed that depletion of TARG1 increased RACK1 MARylation, both by immunoprecipitation-Western and PLAs and stress granule assembly in OVCAR3 cells, as well as two other ovarian cancer cell lines." (PMID 39760726, 2025). "Similarly, in ovarian cancer, PARP14 inhibition suppresses tumor growth by modulating MARylation of receptor for activated C kinase 1 (RACK1) and stress granule formation." (PMID 40741921, 2025). "In ovarian cancer, SMURF2 acts on RACK1, an adaptor protein involved in cancer signaling." (PMID 39697237, 2024). "A comparison of endothelial cells between healthy ovarian and ovarian cancer tissues revealed that genes such as RACK1, S100A6, and C1orf186 were significantly upregulated, while GMB2L1, TM4SF1, and EIF1 were significantly downregulated in the ovarian cancer samples." (PMID 37124501, 2023). "Elevated RACK1 levels in the absence of SMURF2 correlate with poor patient outcomes, positioning SMURF2 as a critical regulator in ovarian cancer progression." (PMID 39697237, 2024).
esophageal squamous cell carcinoma (6 papers, 2016 to 2024). Esophageal squamous cell carcinoma (ESCC) is a type of esophageal carcinoma (EC) that can affect any part of the esophagus, but is usually located in the upper or middle third. "The down-regulation of RACK1 inhibited cell proliferation, invasion and migration of esophageal squamous cell carcinoma in vitro and in vivo, and the expression of RACK1 was negatively correlated with E-cad protein." (PMID 38190388, 2024). "RACK1 induces EMT, further promotes the progression of esophageal squamous cell carcinoma (ESCC) and glioma." (PMID 33194731, 2020).
liver cancer (6 papers, 2011 to 2025). An epithelial or non-epithelial malignant neoplasm that arises from the liver. "We subsequently determined the role of one of these genes, RACK1, which encodes “receptor for activated protein kinase C” (RACK1), in miRNA function, as well as its expression in liver cancers." (PMID 21935400, 2011). "The Kaplan‐Meier database revealed that high RACK1 expression in liver cancer patients was negatively associated with the overall survival, recurrence‐free survival and progression‐free survival, demonstrating that RACK1 is a therapeutic target for liver cancer." (PMID 40836602, 2025). "Compared to those in the non‐carcinoma samples, the RACK1 levels in liver cancer samples were increased." (PMID 40836602, 2025). "RACK1 levels within the tumour tissues of patients with liver cancer were determined." (PMID 40836602, 2025). "It has also been confirmed that RACK1 and ANXA7 are interacting proteins that participate in liver cancer metastasis." (PMID 31474227, 2019).
glioblastoma (5 papers, 2013 to 2025). The most malignant astrocytic tumor (WHO grade IV). "In human U87MG glioblastoma cells, it was found that AChE-R protein variant can support proliferation of glioblastoma tumors by forming a complex with the scaffold protein RACK1 and protein kinase Ce." (PMID 24204383, 2013). "Further supporting the role of RACK1 with the EMT, depletion of RACK1 in glioblastoma cells reduced the expression of EMT markers." (PMID 40940922, 2025).
myeloma (5 papers, 2022 to 2025). "According to the research results of cell type-specific regulatory activity, the most activated TFs in these myeloma cell subgroups included ETV7(C0 GNB2L1+ NK cells), TAF1(C1 RACK1+ NK cells), POU2F2(C2 HNRNPH1+ NK cells), and RUNX2(C3 ATP5E+ NK cells)." (PMID 40454289, 2025). "Screening with a MAPK pathway PCR array and protein‐level detection revealed that Rack1 enhances P38 phosphorylation, similar to its role in multiple myeloma cells." (PMID 38523594, 2024). "In addition, a recent study showed that RACK1 is essential for the proliferation of multiple myeloma cells and that RACK1 silencing also induces an increase in G2/M phase." (PMID 37848434, 2023).
Cerebral ischemia (4 papers, 2013 to 2025). Restriction of arterial blood supply to the brain associated with insufficient oxygenation to support the metabolic requirements of the tissue. "At the same time, the up-regulation of RACK1 reduces infarct size, neuronal death, neuronal tissue loss, and neurobehavioral dysfunction in cerebral ischemia-reperfusion injury." (PMID 38410996, 2024). "In the present study, coimmunoprecipitation data suggest that cerebral ischemia induced the increased binding of nSMase2 with RACK1 and EED, which might have been associated with nSMase2 activation in the early phase of ischemia." (PMID 24007266, 2013). "This study presents evidence from both in vitro and in vivo experiments, indicating an upregulation of RACK1 in MCAO/R‐induced cerebral ischemia‐reperfusion." (PMID 39097918, 2024). "RACK1 exerts neuroprotective effects by preventing neuron death in brain injuries, such as TBI and cerebral ischemia-reperfusion." (PMID 38410996, 2024). "Although enhanced binding of nSMase2 with RACK1 and EED were also observed after cerebral ischemia, nSMase2 activity was not blocked by the TNF-α receptor inhibitor through RACK1/EED signaling." (PMID 24007266, 2013).
amyotrophic lateral sclerosis (3 papers, 2022 to 2024). Amyotrophic lateral sclerosis (ALS) is a neurodegenerative disease characterized by progressive muscular paralysis reflecting degeneration of motor neurons in the primary motor cortex, corticospinal tracts, brainstem and spinal cord. "RACK1 is also related to neurovegetative diseases such as amyotrophic lateral sclerosis (ALS) and Huntington’s disease (HD)." (PMID 39458945, 2024). "However, little is known about the role of RACK1 in the pathogenesis of neurodegenerative disorders, such as amyotrophic lateral sclerosis (ALS) and frontotemporal dementia (FTD)." (PMID 38111057, 2023). "RACK1 also mediates the binding between translational machinery and TDP-43, which is an RBP involved in Amyotrophic Lateral Sclerosis (ALS)." (PMID 36233159, 2022).
cervical squamous cell carcinoma (3 papers, 2020 to 2023). A squamous cell carcinoma arising from the cervical epithelium. "Subsequently, RACK1 was reported to suppress the growth and promote apoptosis of some cancer cells, including colon, gastric and cervical squamous cancers." (PMID 37848434, 2023). "A report have demonstrated that CCNO is overexpressed in cervical squamous cell carcinoma (CSCC) and RACK1/miR-302b/c/d-3p-mediated CCNO inhibition can dampen the progression of CSCC." (PMID 37124622, 2023).
cutaneous melanoma (3 papers, 2008 to 2022). A primary melanoma arising from atypical melanocytes in the skin. "miRNA-124a has been shown to function as a tumor suppressor by targeting Receptor for Activated Protein C Kinase (RACK1) in cutaneous melanoma and the histone methyltransferase Enhancer of Zest Homolog 2 (EZH2) in uveal melanoma." (PMID 35480113, 2022). "To define the distribution pattern of RACK1 mRNA, we performed in situ hybridisation onto pig sections of normal skin, and on samples of cutaneous melanoma and metastatic melanoma samples from lung, liver and lymph nodes." (PMID 18442364, 2008). "We found that RACK1 overexpression characterized cutaneous melanoma in the MeLiM swine model as well as in human patients." (PMID 18442364, 2008). "In summary, RACK1 signal was low in nevi and very much increased in cutaneous melanoma." (PMID 18442364, 2008). "In cutaneous melanoma, nests of MITF+ cells expressed RACK1 protein." (PMID 18442364, 2008).
depression (3 papers, 2015 to 2025). "In stress-related disorders, including depression, a link among GCs, GR, RACK1 and BDNF has been found." (PMID 39846545, 2025). "In the neurobehavioral context, RACK1 has been suggested to promote resilience to chronic stress exposure, thus representing a novel target for the treatment of stress-related disorders, including depression." (PMID 39846545, 2025). "Here, we used them to study the roles of RACK1/NR2B, AKAP/PKA and MAP2/PKA complexes in the RSC and establish whether mechanisms mediating remote fear extinction from other anxiety- and depression-related behaviors can be differentiated at the level of discrete NR2B and PKA signaling." (PMID 26460481, 2015). "Tat-RACK1 and Tat-AKAP enhanced fear extinction, all peptides reduced anxiety and none affected baseline depression-like behavior." (PMID 26460481, 2015).
Down syndrome (3 papers, 2011 to 2023). "Increased RACK1 expression has also been observed in the frontal cortex of patients with bipolar disorder, while decreased RACK1 expression is reported in the cortex of Down syndrome patients." (PMID 21978545, 2011). "Recently, very exciting data published by the Lebel group suggests that depletion of Werner syndrome, RecQ helicase-like (WRN) protein in the nucleus causes RACK1 to move out of the nucleus and to collocate with PKCβII and PKCδ." (PMID 21978545, 2011). "A decrease in RACK1 was reported in the cortex of down syndrome patients." (PMID 36691005, 2023).